SATB1 (SATB homeobox 1)
Diseases named in the same sentence as SATB1 in open-access papers (continued):
Sharing a sentence is not in itself a finding about the gene and the disease.
tumor (continued). "Among the 69 tumor specimens tested, the relative SATB1 mRNA level (tumor tissue vs. matching unchanged mucosa of CRC patients) was decreased in 51 (73.9 %) tumors while it was increased in 18 (26.1 %) cases." (PMID 25874491, 2015). "SATB1 mRNA level in tumor tissues was over twofolds lower than in samples of corresponding unchanged tissues and fourfolds lower than in biopsies of healthy colon mucosa." (PMID 25874491, 2015). "The average content of SATB1 protein in tumor tissue was similar to that in unchanged mucosa of the large intestine of CRC patients (6.23 ± 0.86 vs. 5.42 ± 0.89, respectively; P = 0.56)." (PMID 25874491, 2015). "To assess SATB1 expression in tumor and unchanged mucosa at the protein level, we used also Western blotting method." (PMID 25874491, 2015). "In other words, it can be interpreted that high tumor proliferative rate, measured by Ki67 expression, in the context of low SATB1 (and relatively low HIF-1α) expression was an independent predictor of worse OS." (PMID 26512778, 2015). "Immunohistochemical staining demonstrated higher nuclear and cytoplasmic SATB1 reactivity in the tumor tissue compared to unchanged mucosa of CRC patients." (PMID 25874491, 2015). "SATB1 protein content in both tumor and unchanged tissue samples of CRC patients was significantly higher than the amount of SATB1 protein in colonic biopsies of the healthy group (6.23 ± 0.86 and 5.42 ± 0.89 vs. 1.00 ± 0.13, respectively; P < 0.0001)." (PMID 25874491, 2015). "Among 32 tumor tissue specimens tested, the relative content of SATB1 protein (tumor tissue vs. matching unchanged mucosa of CRC patients) was downregulated in 15 (46.9 %) tumors while it was upregulated in 17 (53.1 %) cases." (PMID 25874491, 2015). "Immunohistochemical examination of SATB1 expression included two sub-analyses: total 102 tumor cases vs. 39 unchanged colon tissues of CRC patients and matched tumor vs. normal colon samples from 39 CRC patients." (PMID 25874491, 2015). "Western blotting analysis revealed that SATB1 protein content in tumor and unchanged tissues of CRC patients was over sixfold and fivefolds higher than in biopsies of healthy colon mucosa, respectively." (PMID 25874491, 2015). "ATM, which expresses in a variety of tumor, is commonly considered as a tumor suppressor for its role in DNA damage repair machinery and in SATB1-induced tumorigenic progression." (PMID 26528698, 2015). "It was described in our results above that SATB1 or HER2 single positive expression correlated with tumor histological grade." (PMID 25956130, 2015). "Immunohistochemical analysis of 560 CRC specimens showed that SATB1 expression was significantly higher in CRC tissues than in matched non-tumor mucosa (p<0.001)." (PMID 24971456, 2014). "Tumor formation in the liver and spleen was significantly promoted by SATB1 expression in CRC cells." (PMID 24971456, 2014). "Using a combined variable wherein SATB1 expression of any intensity in >1% cells in the primary tumour and/or metastases was denoted as positive, 21 (19.8%) PB-type cases had positive and 85 (80.2) cases had negative SATB1-expression." (PMID 25323550, 2014). "Expression of SATB1 has been correlated with a more aggressive tumor phenotype and worse prognosis in cancer of the breast, ovary, colorectum, and larynx." (PMID 25326863, 2014). "SATB1 overexpression increased tumor growth and metastasis to lung and liver in vivo by using xenograft animal models (p<0.05)." (PMID 24971456, 2014). "An in vitro study supported the correlation between SATB1 expression and aggressive tumor behavior and also suggested that SATB1 plays a role in multidrug resistance." (PMID 25326863, 2014). "Special AT-rich sequence binding protein 1 (SATB1) has regulatory effects on gene expression and appears to play an important role in tumor progression." (PMID 24932280, 2014).
tumor (continued). "SATB1 appears to play an important role in transforming the gene expression profile of tumor cells to have invasive and metastasizing properties, and knockdown of SATB1 has been demonstrated to result in the reversion of distant metastases." (PMID 24932280, 2014). "SATB1 remained significant as a prognostic factor when tumor location was included in the adjusted Cox regression model, indicating that SATB1 is prognostic in upper gastrointestinal tract cancer regardless of its anatomical location." (PMID 25326863, 2014). "SATB1 was often heterogeneously expressed and the number of positive cells was often low, which justifies assessment not only of the primary tumour, but also metastases in order to improve the detection of positive cases." (PMID 25323550, 2014). "The spleen tumor weights weighed 0.242±0.1 g and 0.146±0.03 g in the SATB1-overexpressing group and the empty vector control group, respectively." (PMID 24971456, 2014). "We found SATB1 to be an independent prognostic factor in patients with a radically resected tumor, correlating with shorter overall survival as well as with shorter recurrence-free survival." (PMID 25326863, 2014). "Positive expression of SATB1 was denoted in 16/106 primary pancreatobiliary type tumours and 11/65 metastases, and in 15/63 primary intestinal type tumours and 4/26 metastases, respectively." (PMID 25323550, 2014). "The findings from the present study thus provide further evidence of SATB1 being a master regulator towards a more aggressive tumour phenotype and a biomarker of poor prognosis in human cancer." (PMID 25323550, 2014). "SATB1 promotes tumor metastasis by providing a nuclear architectural platform regulating the expression of >1000 genes, many of which are related to cell growth and translocation." (PMID 24047082, 2013). "Specifically, SATB1 has been shown to induce the expression of tumor and metastasis-promoting genes while suppressing the expression of metastasis suppressor genes." (PMID 24260116, 2013). "Recently, accumulating data suggests that over-expression of SATB1 contributes to tumor progression." (PMID 24047082, 2013). "Mechanistically, the effects of miR-191 and miR-425 on tumor growth and invasion require, at least in part, the suppression of SATB1, CCND2 and FSCN1." (PMID 23505378, 2013). "In this study, we showed that the enhanced HLA class I expression in EBV+ cHL is positively associated with the number of PML-NBs and inversely correlated with the nuclear staining intensity and the percentage of SATB1 positive tumor cells." (PMID 24009715, 2013). "Frequency of SATB1 expression was higher in poorly differentiated adenocarcinoma (84.6%) than in well and moderately differentiated neoplasms (51.9%, P = 0.035)." (PMID 23326301, 2013). "SATB1 expression also showed significant differences with depth of tumor invasion (T1+T2 vs. T3+T4, 48.4% vs. 65.3%, P = 0.024) and with pTNM stage (stage I+II vs. III + IV stages (62.5% vs. 77.1%, P = 0.047)." (PMID 23326301, 2013). "Ectopic expression of SATB1 is shown to induce tumor-like morphology in 3D culture and lead to tumor formation and lung metastasis in nude mice." (PMID 24040146, 2013). "Conversely, knockdown of SATB1 in the highly invasive MDA-231 cells had the opposite effect: tumor/metastasis promoting genes were downregulated whereas inhibitors of these processes were upregulated." (PMID 24260116, 2013). "Multivariable analysis indicated that the number of PML-NBs is the most significant independent factor correlating with HLA class I expression in EBV+ cHL, while the percentage of SATB1+ tumor cells also had an independent effect." (PMID 24009715, 2013). "SATB1 is involved in tumor progression and has been suggested to be an independent prognostic factor." (PMID 23326301, 2013).
tumor (continued). "The percentage of SATB1 positive cells varied between 0% to 100% in tumor cells and was inversely correlated with the level of HLA class I expression, but only between normal and strong expression (p<0.05)." (PMID 24009715, 2013). "SATB1 is highly expressed in many types of human cancers and up-regulation of SATB1 expression is essential for tumor survival and metastasis, thus SATB1 represents one of such ideal TAAs." (PMID 23437226, 2013). "The expression level of SATB1 showed correlation with tumor differentiation and pTNM stage, and SATB1 was also associated with the expression of various biologic markers (including Cyclin D1, MMP-2, NF-κB, PCNA, APC and BRAFV600E)." (PMID 23326301, 2013). "Multivariable analysis indicated that the number of PML-NBs and the percentage of SATB1+ tumor cells are independent factors affecting HLA class I expression in EBV+ cHL." (PMID 24009715, 2013). "We analyzed HLA class I, number of PML nuclear bodies (NBs) and SATB1 expression in tumor cells of 54 EBV+ cHL cases and used 27 EBV− cHL cases as controls." (PMID 24009715, 2013). "Ectopic expression of SATB1 in MCF10A-1 induced tumor-like morphology in three-dimensional cultures, led to tumor formation in immunocompromised mice, and when injected into tail veins, led to lung metastasis." (PMID 23251624, 2012). "This study provides further evidence of important regulatory functions of SATB1 in ovarian carcinogenesis and progression, and demonstrate SATB1 expression to be an independent factor of poor prognosis in high-grade tumours." (PMID 22992394, 2012). "A limitation to the here analyzed cohort is the lack of information on residual tumour after surgery, and therefore, the prognostic value of SATB1 expression in EOC should be confirmed in studies on tumours for which this information is available." (PMID 22992394, 2012). "These in vivo data indicate that the SATB1 expression level is critical for tumor progression; whereas low levels of SATB1 expression are sufficient for tumor formation, higher levels of SATB1 are necessary for lung metastasis of MCF10A-1 cells." (PMID 23251624, 2012). "In the present study, immunohistochemical SATB1 expression was examined in primary tumours from 151 incident cases of EOC from two Swedish population-based cohort studies, and correlated with clinicopathological factors, molecular parameters, and survival." (PMID 22992394, 2012). "Spearman ́s Rho test was used for comparison of SATB1 expression (nuclear score) with clinicopathological and tumour biological factors." (PMID 22992394, 2012). "Following antibody optimisation and staining, SATB1 expression was successfully annotated in 529 (95.0%) tumours and beta-catenin in 527(94.6%) tumours." (PMID 22935204, 2012). "Immunohistochemical expression of SATB1 was examined in tissue microarrays with tumours from 151 incident EOC cases from two prospective, population-based cohorts." (PMID 22992394, 2012). "A strong, signficant association was however seen between SATB1 expression and MSS tumours (p = <0.001), beta-catenin overexpression (p = <0.001) and SATB2 expression (p = <0.001)." (PMID 22935204, 2012). "In sum, our results demonstrate a strong oncogenic role for SATB1 in immortalized cells under a permissive gene expression profile and uncover a tumor suppressive role for ATM in preventing SATB1-mediated oncogenesis." (PMID 23251624, 2012). "The factor 1 (SATB1/HIF-1α-AR/ER/BCL2) pattern in the HR-positive tumours revealed an inverse relation between the two groups of markers with the opposite factor loadings." (PMID 22424533, 2012). "SATB1 is not only expressed in tumour cell nuclei, but also in stromal lymphocytes, serving as internal staining controls, and our results demonstrate that the prognostic impact of SATB1 was evident even at low levels of expression." (PMID 22992394, 2012).
tumor (continued). "Six of these non-previously reported variations were encountered in more than one tumor sample, and were confined to three genes, one in SATB1, four in MUC5AC and one in DDX26B." (PMID 21698250, 2011). "In contrast to SATB1, tumours classified as having higher transcript levels of SATB2 were significantly associated with a poorer OS." (PMID 19642980, 2009). "In addition, this possibility is further supported by recent evidence demonstrating that the nuclear protein SATB1 acts as a 'genomic organiser' involved in the epigenetic remodelling of chromatin to facilitate upregulation of metastasis-associated genes and down-regulation of tumour suppressors." (PMID 18590575, 2008). "Considering the downregulation of SATB1 in tumor-infiltrated exhausted CAR-T cells, we investigated whether SATB1 overexpression could enhance CAR-T cell functionality." (PMID 41372119, 2025). "Additionally, tumor-derived transforming growth factor β decreased SATB1 expression through promoting the binding of Smad proteins to the Satb1 promoter." (PMID 40071088, 2025). "Importantly, SATB1-CAR-T cell therapy significantly extended the survival of tumor-bearing mice, with over 50% surviving beyond 100 days post-infusion." (PMID 41372119, 2025). "In ESCC, triptolide exerts anti-tumor effects via the circNOX4/miR-153-3p/SATB1 axis." (PMID 41208974, 2025). "Notably, tumor-infiltrating CD8+ T cells from SATB1-CAR-T group exhibited 50% lower PD-1, CTLA-4, TIM3, and LAG-3 expression compared to controls, aligning with their exhaustion-resistant phenotype in vitro." (PMID 41372119, 2025). "Additionally, SATB1 knockdown in NSCLC cells downregulates tumor-promoting genes like c-myc, MMP2, MMP9, S100A4, and VEGF-B while also reducing the expression of EMT-related genes (e.g., N-cadherin, fibronectin) and inhibiting the Wnt/β-catenin pathway." (PMID 40071088, 2025). "Additionally, SATB1 silencing using RNA interference techniques, including siRNA and shRNA, has demonstrated the ability to inhibit tumor cell proliferation and invasion in preclinical models, positioning SATB1 as a promising therapeutic target." (PMID 40071088, 2025). "• SATB1 expression increases and correlates with tumor progression and metastasis." (PMID 40071088, 2025). "• SATB1 expression increases and correlates with tumor differentiation." (PMID 40071088, 2025). "Moreover, multiple signaling pathways contribute to the anti-tumor effects of Huangqin, such as NF-κB, Wnt/β-catenin, SATB1, Bcl-2 family proteins, Caspase, PI3K/Akt, mTOR, ERK, p38-MAPK, TGF-β/Smad, and Hippo/YAP pathways." (PMID 38993643, 2024). "Special AT-rich sequence-binding protein-1 (SATB1) is a transcriptional regulator and genome organizer with the ability to regulate hundreds of genes, for which interest has increased in recent years as a tumor marker." (PMID 39195213, 2024). "Furthermore, our study reveals a sequential transcription activation mechanism that leads to Twist1-inducible SATB1 transcription and SATB1-inducible OPN transcription, providing molecular insight into SATB1-mediated tumor immunity." (PMID 38416830, 2024). "SATB1 is crucial for the transition from DP to SP cells, so in individuals with SATB1 deficiency, the generation of CD8+ T cells is reduced, the expression level of PD-1 is increased, tumor immunity is suppressed, ultimately leading to cancer development." (PMID 38586584, 2024). "Owing to weak co-stimulation and tumor microenvironment signaling, TGFβI may reduce Satb1 induction, thereby increasing PDCD1 levels and further locking T-cell in a depleted state." (PMID 37091977, 2023). "Special AT-rich sequence-binding protein-1 (SATB1) might have diverse functions in cancer dependent on tumor type and stage." (PMID 35125116, 2022). "This underlines the duality of SATB1 function in cancer depending on the cell type in which it is expressed (selective expression in tumor cells and not in the surrounding tissues)." (PMID 35812421, 2022).
tumor (continued). "Research into this also showed that SATB1 was rather only expressed in some carcinoma cells and in some patients and not in all cell types from the tissues examined, hence providing insight into the heterogeneity of tumor progression and metastasis potential." (PMID 35812421, 2022). "A continuous increased expression of SATB1 has been described to convert inflammatory anti-tumor DCs into pro-tumor DCs by enhanced secretion of pro-tumorigenic cytokine IL-6 and immunosuppressive factor Galectin-1, activating immune-evasive pathways in these cells." (PMID 33761971, 2021). "Additionally, in vivo silencing of Satb1 expression in tumor-associated DCs was found to diminish immunosuppression in the TME, boost T-cell mediated anti-tumor activity and delay tumor progression." (PMID 33761971, 2021). "Previously, the effects of SATB1 acting as a tumor promoter had been demonstrated." (PMID 34604093, 2021). "Furthermore, STAT5 overexpression downregulates STAT4 and SATB1 expression through the induction of microRNA-155 (miR-155), empowering tumor immune response escape mechanisms and decreasing the secretion of anti-tumor molecules, such as IFNγ." (PMID 34685762, 2021). "Still, however, major differences were seen between different cell lines, indicating that more subtle differences in the molecular or cellular context of the tumor cell may determine to what extent SATB1 expression is pivotal in HNSCC tumorigenesis." (PMID 32451408, 2020). "SATB1 has also been under investigation in the cancer research field due to its high expression in several malignancies, supporting its action as a tumor promoter." (PMID 33356851, 2020). "Intratumoral CD8+SATB1+ cell density predicted better OS and could potentially serve as a specific biomarker of anti-tumor immunity." (PMID 32612954, 2020). "The independent prognostic significance of CD8+SATB1+ cells infiltrating the tumor could indicate their role in anti-tumor immunity." (PMID 32612954, 2020). "In fact, this might explain different sensitivities of tumors/ tumor cells towards SATB1 inhibition." (PMID 32451408, 2020). "Gene expression experiments have confirmed that SATB1 regulates around 300 of T cell genes and initial studies have indicated that SATB1 might play a vital role in anti-tumor T cell responses." (PMID 32612954, 2020). "Thus, it can be concluded that the observed tumor-inhibitory effects rely on both, anti-proliferative and pro-apoptotic effects of SATB1 knockdown." (PMID 32451408, 2020). "Multiple Cox regression analysis revealed three independent predictors of the patient's overall survival: Haralick's texture entropy of PR (HR = 0.19, p = 0.0005), Ki67 Ashman's D bimodality (HR = 3.0, p = 0.01), and CD8+SATB1+ cell density in tumor tissue (HR = 0.32, p = 0.02)." (PMID 32612954, 2020). "Therefore, in T cell specific Satb1 deficient mice, PD1 is expressed at high levels and tumor immunity is impaired." (PMID 33356851, 2020). "The transient nature of siRNA therapies, however, may be well suited for handling those while exploring the desired effects of SATB1 knockdown in tumor cells, benefitting from its actions on several molecular targets in parallel." (PMID 32451408, 2020). "This is in line with the notion of SATB1 affecting the expression of many genes, as to be readily expected from its broader molecular mechanism(s) of action as chromatin organizer and in other tumor entities." (PMID 32451408, 2020). "Similarly, Wang and co-workers observed that SATB1′s expression positively correlated with the size and grade of the tumour, the presence of lymph node metastasis, the stage of the disease and the tumour ER status." (PMID 31450715, 2019). "Moreover, a high SATB1 level was associated with the SCC histological type, poor tumour differentiation and an early stage of the disease." (PMID 31450715, 2019).